IFNG (interferon gamma)
Diseases named in the same sentence as IFNG in open-access papers (continued):
Sharing a sentence is not in itself a finding about the gene and the disease.
tumor (continued). "Furthermore, this metabolic dysregulation is also mediated by pro-inflammatory cytokines originated by tumor by-products, as well as by the host immune system, in which tumor necrosis factor (TNF-α), interferon-gamma (IFN-γ), and several interleukins, including IL-6, are involved." (PMID 35457471, 2022). "Mechanistically, the authors showed that activated CD8 T cells released the effector cytokine, interferon gamma (IFNγ), which upon binding to cancer cells triggered the downregulation of SLC7A11 expression, thereby impairing cystine uptake and resulting in lipid peroxidation and tumor ferroptosis." (PMID 35065965, 2022). "To determine whether PD-1 was blocking T cells that might have otherwise expressed IFNγ, we treated mice containing or lacking NK cells with anti-PD-1 starting on D3 after tumor implantation and harvested on D7." (PMID 36531040, 2022). "IFNγ treatment block M-MDSC to produce the tumor-promoting molecule nitric oxide (NO) and PGE2, which promote nuclear accumulation of P50 NF-κB in M-MDSCs, indicating that IFNγ treatment may reverse NO-mediated immunosuppression of MDSCs through PGE2/NO/P50 pathways." (PMID 36131911, 2022). "We found that IFNγ -stimulated NK cells and macrophages, but not B cells, could induce a tumor cell-in-cell formation, albeit at a lower percentage compared to activated T cells." (PMID 36124553, 2022). "The M1 activation induced by lipopolysaccharide (LPS) or cytokines such as interferon-gamma (IFN-γ) and tumor necrosis factor-alpha (TNF-α), is characterized by high antigen presentation capacity, the killing of intracellular pathogens, secretion of pro-inflammatory cytokines and anti-tumor effects." (PMID 35625939, 2022). "Thus, it is not suitable to use IFN-γ to represent the anti-tumor activities of TGFβ/IFNγ-producing CD4 T cells." (PMID 36289759, 2022). "Interestingly, these three lymph nodes showed high IFNγ secretion in no stimulation condition with tumor cells (as negative controls) at the same experiment." (PMID 35606862, 2022). "CD4+ have been previously observed to be the primary mediators of tumor clearance in a manner that is independent of CD8+ T cells but reliant on IFNγ, and the partnership between CD4+ T cells and macrophages has been documented as one of the mechanisms driving this effect." (PMID 36123677, 2022). "Interestingly, the absence of IFNγ completely abolished the high antitumor capacity induced by IL-12+IL-18 expression, indicating an important role for these cytokines in early tumor growth control." (PMID 36330506, 2022). "The variation in IFNγ levels observed between TIL cultures does not appear to be driven by the tumour subtype derived cultures, but perhaps, there are patient-specific factors that may affect the innate cytotoxic capacity of TILs." (PMID 35158816, 2022). "Further, we found that 4MOSC1-LucOS tumor-bearing animals having experienced a complete response to αCTLA-4 ICI therapy harbor OVA-Tet+ CD8 T cells that respond robustly to rechallenge with SIINFEKL-loaded bone marrow-derived dendritic cells, as assessed by IFNγ ELISpot assays." (PMID 35879302, 2022). "Moreover, two signatures for assessing the ability to release IFN-γ, IFNG, and Merck18 both suggest that the patients of the low-MRGPI subgroup have a stronger IFN-γ release ability, which indirectly reflects that they have a stronger tumor-killing effect." (PMID 35844514, 2022). "Taken together, these results demonstrated that Vγ2 x PD-L1 could redirect Vγ2Vδ2 T cells to kill PD-L1+ tumor cell lines with IFNγ secretion, but to leave PD-L1 negative tumor cells and healthy cells un-attacked." (PMID 35784353, 2022). "In the same study it was found that PD-L1 + tumor cells generated in the context of activated TAMs were resistant to chemotherapeutic regimens and therapy with ICI, whereas PD-L1 + tumor cells in the context of activated T-cells producing IFNγ, were sensitive to ICI." (PMID 33498238, 2021).
tumor (continued). "According to these results, we speculate that T cells that express IL-32 may have a contradictory role that promotes IFNγ expression in CD8+ T cells, which enhances the antitumor activity, and induces CD4+ T cells Foxp3 expression, which suppresses tumor immune response." (PMID 34414188, 2021). "This was manifested by an increase in CD8+ TIL cells, Neutrophil (Ly6G + cells), tumor-specific T cells, Dendritic cells (CD11c+), high-mobility group box 1 (HMGB1), and activated CD8+ T cells (as indicated by intracellular interferon gamma (IFNγ) expression)) at 7–10 days post-treatment." (PMID 33827375, 2021). "YIV-906 could potentiate the IFNg activity to turn up the signaling transduction response to a higher level; as anti-PD1 alone could activate T cells which released IFNg in tumor, adding YIV-906 could further amplify the IFNg signal and enhance M1-like macrophage polarization." (PMID 34188068, 2021). "To examine whether the PD-L1 pathway is blocked by ICT in LLC tumour tissues, we examined the PD-L1 expression by immunoblotting, but found that ICT upregulated the PD-L1 expression, which may be induced by upregulated IFNG in TME." (PMID 33460401, 2021). "IL-32 may have a contradictory role in the TME such as it promotes IFNγ expression in CD8+ T cells, which enhances the antitumor activity, but at the same time induces Foxp3 expression in CD4+ T cells, which suppresses the tumor immune response." (PMID 34414188, 2021). "Factors that can promote the anti-tumor neutrophil phenotype include chemokines (e.g., CXCL2, CXCL5, CXCL8, CCL2, CCL3, CCL5, CXCL12 (SDF-1), CXCL16 and IL-8) alone or together with G-CSF/GM-CSF, TNFα, IFNβ, IFNγ, IFNγ together with TNFα, Resolvin D1, hepatocyte growth factor (HGF) and IL-17." (PMID 34572138, 2021). "Phenformin led to a 30% reduction in tumor growth in IFNγ+/+, and not IFNγ−/−, animals." (PMID 34083537, 2021). "Given that expression of both CD74 and PD-L1 can be induced by proinflammatory cytokines such as IFNγ, it is possible that the association we found simply reflects the presence of cytokines produced by activated CD8+ T cells in the tumor microenvironment, rather than a functional relationship." (PMID 34944801, 2021). "IFNG (interferon gamma, INFγ)released from CD8+ T cells downregulates the expression of SLC3A2 and SLC7A11, two subunits of the glutamate-cystine antiporter system xc-, inhibits the uptake of cystine by tumor cells, and consequently promotes tumor cell lipid peroxidation and ferroptosis." (PMID 34422642, 2021). "Furthermore, T cell effector function was evaluated by quantifying the release of immunostimulatory cytokine interferon-gamma (IFN- γ), which is involved in the anti-tumor cytotoxic T cell response 32, and by evaluating cancer cell killing by T cells in co-cultures." (PMID 33972919, 2021). "When released into tumor microenvironment, ATP acts on P2X7 purinergic receptors and triggers the NOD-like receptor family, pyrin domain containing-3 protein (NLRP3), allowing for the secretion of interleukin-1beta (IL-1β) then primes IFNγ-producing tumor antigen-specific CD8+ T cell in mice." (PMID 34094967, 2021). "Furthermore, the considerably unregulated expression of TNFα, IFNγ, and CD107a was aborted in the absence of tumor cells even under the stimulation by Y111." (PMID 34040604, 2021). "To this end, we first assessed the reactivity of tumor-infiltrating lymphocytes (TILs) isolated from untreated SMA560 tumors to 12 top-predicted MHC I-restricted neoepitopes (IEDB MHC I percentile rank score ≤0.4), which included Odc1MHC I, using the IFNγ ELISpot assay." (PMID 33462231, 2021). "These tumour-infiltrating Tregs consisted of a FoxP3hi population suppression-competent population, and a second poorly suppressive FoxP3lo population that was induced by the TH1-polarising cytokine IL-12 and that also secreted the pro-inflammatory cytokines IFNγ and IL-17." (PMID 32457487, 2021).
tumor (continued). "This suggests a potential difference in the regulation of HDACs between individuals in response to IFNγ, although in this small group, the sensitivity could not be related to differences in tumor genetics." (PMID 34439300, 2021). "Subsequently, transfection of tumor cells with genes coding for cytokines that promote antigen presentation (discussed later), activate T cells and APC or induce costimulatory molecules (IFNγ, IL-2, IL-4, IL-7, GM-CSF) were shown to increase tumor immunogenicity and elicit antitumor immunity." (PMID 33671123, 2021). "However, this vaccine failed to induce regression of established tumor because it also up-regulated PD-1 expression on tumor cells dependent on IFNγ and up-regulated PD-1/Tim-3 expression on CD8+ TILs." (PMID 33753998, 2021). "The survival benefit was accompanied by a significant infiltration of IFNγ-, Granzyme B-, and TNFα-secreting effector T-cells, demonstrating that the combined use of CD40 agonist and PD1 antagonist antibodies can reprogram immune resistant tumors in favor of anti-tumor immunity." (PMID 34201127, 2021). "Identification of an IL-10 response in the absence of any IFNγ to citCp450 indicates that in addition to the Th1 responses a potential regulatory repertoire exists in the mice to a citrullinated self-antigen that is presented by B16 tumour." (PMID 34858415, 2021). "Our data demonstrated a significant inhibitory effect of SFV/IFNg without Pam3 compared to that of the PBS group (last day tumor volume p = 0.004 and the tumor weight p = 0.0079) and to the SFV/Luc group (last day tumor volume p = 0.0159 and the tumor weight p = 0.0476)." (PMID 34835178, 2021). "Finally, and unexpectedly, we identified a “paradoxical” subgroup of CRC (n = 33/96 (34%)) that did not display any IFNγ response although they produced mature IL-18 and featured aCasp1+ tumor cells in 50% of cases." (PMID 33430344, 2021). "This 45-nucleotide long aptamer could recognize both murine and human PDL1 and modulate the tumor microenvironment by elevated CD4+ and CD8+ T cell infiltration and IL2, IFNγ, TNFα and other chemokine expression at the tumor site, which might form a loop against tumor proliferation." (PMID 34575825, 2021). "We hypothesized that addition of IL-18, which can induce the proliferation of several immune effector cells through inducing IFNγ, major histocompatibility complex (MHC) class I expression, and also by inhibiting angiogenesis, could synergize with IL-27 to enhance tumor growth control." (PMID 34209203, 2021). "Among those, some are tumor-intrinsic factors, such as a lack of neoantigens, epigenetic changes in cancer cells (that can alter the expression of immune-related genes), alteration of signaling pathways, and regulation of interferon-gamma pathway." (PMID 33805461, 2021). "Notably, similar antigen-specific IFNγ secretion was observed for both, the CXCR5 CAR-T as well as the CD19 CAR-T cells, although CD19 expression levels were on average 5–10-times higher than for CXCR5 on all tumor cell lines." (PMID 33431832, 2021). "Furthermore, T cell-related genes such as CD8A/B, PD-L1, LAG3 and IFNG were not more highly expressed in anti-PD-1-responsive tumours." (PMID 34885021, 2021). "In addition to tumor IFNG signal, inhibiting the IFN-I signal in tumor cells might also reduce the expression of drug resistance-related genes." (PMID 35154340, 2021). "It inhibited orthotopic bladder tumors, orthotopic breast tumors and lung metastasis, and Neuro-2A tumor growth both in injected and contralateral sites to a significantly greater extent than oHSV-1 Baco-1 (γ34.5Δ), while inducing more active tumor-specific CTL and IFNγ secretion." (PMID 34578321, 2021). "Mechanistically, CD8+ T cell-derived IFNγ inhibits SLC7A11 expression in cancer cells through activating the transducer and activator of transcription 1 (STAT1), thereby inducing tumor cell ferroptosis and contributes to the anti-tumor efficacy of immunotherapy." (PMID 34796174, 2021).
tumor (continued). "In addition, other immune system pathways, such as interferon gamma signaling and regulation of cytokine production was also found, suggesting that RNF135 may have potential effects on anti-tumor immune and immune therapy." (PMID 35145901, 2021). "Enrichment analysis demonstrated that these anti-cancer herbs may prevent from tumor immune evasion through regulating immune system processes such as TRIF-dependent toll-like receptor signaling pathway (q = 0.0189) and interferon-gamma-mediated signaling pathway (q = 3.48 × 10–4)." (PMID 33558586, 2021). "Moreover, chemokines involved in infiltration can be species-specific, limiting efficient trafficking, i.e., human IFNγ secreted for T cells, a cytokine important for tumour elimination, does not act on murine tumour stromal cells." (PMID 34831165, 2021). "It has previously been shown that Nr2f6−/− T cells are hyper-reactive in regard of cytokine production (IL-2, IFNγ, TNFα) as those cytokines are direct target genes of NR2F6-dependent transcriptional repression leading to an improved anti-tumor immune contexture at the tumor site." (PMID 31937317, 2020). "The treatment increased the expression of IFNγ and CXCL9/CXCL10 in the tumor, as well as increased serum IFNγ/TNFα and expression of tumor-infiltrating lymphocytes, which may indicate the effectiveness of durvalumab/olaparib combination therapy in inducing an immune response in the tumor." (PMID 33327450, 2020). "However, a non-significant increase in IFNγ levels was detected in the conditioned medium from tumours derived from histamine-treated mice." (PMID 31748740, 2020). "Although cancer cells themselves are known to hyper-methylate their own IFNγ promoter and thus promote tumorigenesis, it was not known whether this gene is dysregulated in tumor-specific CTLs, especially at the level of DNA methylation." (PMID 32194559, 2020). "As PD-L1TC is induced by pro-inflammatory cytokines, such as IFNγ and TNFα produced by activated T cells, the reaction of tumour cells to the anti-tumour immune response of the host may not always be concordant among intratumoural locations." (PMID 31761900, 2020). "The repression of tumour growth was accompanied by the significant infiltration of mCherry+ CD8+ HER‐2 CAR T cells into tumours; infiltrating HER‐2 T cells exhibited increased cytotoxic capacity (as assessed by IFNγ and TNF expression after PMA/ionomycin treatment ex vivo) (Fig EV5F)." (PMID 31803974, 2020). "We describe that moDCs stimulated by tumor supernatant of the highly cytotoxic NB-PDT condition are able to provide the adequate stimulatory signals for the proliferation of CD4+ T cells and differentiation towards Th1 CD4+ effector T cells, as indicated by the substantial release of IFNγ." (PMID 32326519, 2020). "Fourth, high iron concentrations in the microenvironment of tumor infiltrating lymphocytes may impair IFNγ output by direct negative effects on the transcription or translation of cytokine genes and mRNAs, respectively." (PMID 33344239, 2020). "In addition, NK cells produce proinflammatory cytokines like interferon gamma (IFNγ) and tumor necrosis factor alpha (TNF) upon encountering a target cell, thereby inducing direct as well as indirect anti-tumor effects like the activation and differentiation of naïve T cells." (PMID 33123121, 2020). "Moreover, in a MC38 tumor model, response to anti-PD-1 was dependent on intratumoral cDC1 production of CXCL9 and subsequent signaling through CXCR3 on T cells, which promoted proliferation and production of IFNγ, TNFα, and Granzyme B." (PMID 33584701, 2020). "The IFNγ transcript peaked at 1 h post activation and then declined for all the CTLs, therefore indicating that cytokine induction is diminished, not delayed, in tumor-specific CTLs." (PMID 32194559, 2020).
tumor (continued). "Since the duration of tumor IFNγ signaling and overexpression of ISG.RS accounted for the resistant to ICIs,20 21 we hypothesized that SOX2 impaired CD8+ T-cell killing through regulating the IFNγ signaling." (PMID 33158915, 2020). "The absence of IL-30 in the host environment might slow down tumor growth by preventing Treg expansion and immunosuppressive functions, and by skewing the cytokine milieu towards a Th1-type, IFNγ- and IL-12-driven, immune response." (PMID 32143355, 2020). "The number of macrophages and levels of IFNγ and macrophage inflammatory protein-1β (CCL4) mRNA, were markedly reduced in tumors from CHOP KO mice as compared to wild-type mice, suggesting a role for CHOP in modulating the tumor microenvironment and macrophage recruitment to the tumor." (PMID 32560326, 2020). "Besides their known tumor suppressive properties in CLL, miR-29 family members are also regulators of the adaptive immune system, since they regulate helper T-cell development and interferon gamma (IFNγ) secretion by Type 1 helper T-cells." (PMID 33381116, 2020). "Enhanced EMT features after exposure to inflammatory cytokines (i.e., TGF-β, interferon gamma (IFN-γ) and TNF-α) can impact proliferation, differentiation and apoptosis of natural killer cells (NKs) and T and B cells, suggesting the importance of EMT in the tumor immune microenvironment." (PMID 33348546, 2020). "However, the NK cells that remained at the tumor site were no longer cytolytic, as these cells expressed lower levels of interferon-γ (IFNγ) (p < 0.05)." (PMID 32457755, 2020). "Although, NK cells may lose the ability to produce IFNγ, our results suggest that unlike tumor, overstimulation and persistent HCV infection, they are also gaining function that negatively regulates the adaptive response to chronic T. gondii infection." (PMID 32733814, 2020). "Moreover, when tumor-bearing mice were injected with αGC, intratumoral DCs and iNKT cells showed less STAT6 phosphorylation and IFNγ production, respectively, than cells from the spleen, although similar production of IL4 was detected for the intratumoral iNKT cells and splenic iNKT cells." (PMID 31160756, 2020). "Intriguingly, IFNγ released from CD8+ T cells downregulates the expression of SLC7A11 and of SLC3A2, another subunit of the glutamate-cystine antiporter system (xCT), henceforth, limiting the uptake of cystine by tumor cells, promoting tumor cell lipid peroxidation and ferroptosis." (PMID 32516941, 2020). "Also, IFNs have been shown to regulate PD-L1 expression on tumor and non-tumor cells, whereby IFNγ seems to be the strongest inducer." (PMID 32486375, 2020). "While this assumption may not hold in all model systems, the presence of IFNγ in the tumor was dependent on CD8 + T cell activation." (PMID 31914948, 2020). "Another study found that when IFNγ expression by CD8+ cells increased in the tumor site after irradiation, this also increased PDL-1 expression on tumor cells, ultimately leading to exhausted CD8+ cells, and so αPDL-1 could be considered an appropriate treatment." (PMID 32287292, 2020). "In our setting, treatment of mice bearing an immunogenic tumor (EG.7-OVA) with anti-PDL1 and anti-PDL2 Abs increased the frequency of circulating IFNγ-secreting CD8+ T cells but had scarce effect on tumor-specific immunity and no therapeutic advantage over placebo." (PMID 32290265, 2020). "Furthermore, IFNγ, produced by activated CTLs and abundant in inflamed tumours, can induce CXCL9 and CXCL10 secretion in various intermediary cells, including tumour-infiltrating myeloid cells, which may enhance the role of CXCR3 in homing." (PMID 33046212, 2020). "Additionally, no CAR-mediated IFNγ production was observed after stimulation with the panel of tumour cell lines expressing mMA." (PMID 32429338, 2020).